CXCR4 (C-X-C motif chemokine receptor 4)
Diseases named in the same sentence as CXCR4 in open-access papers (continued):
Sharing a sentence is not in itself a finding about the gene and the disease.
breast carcinoma (continued). "Mir-222 regulates the macrophage migration in breast cancer through the CXCR4 pathway." (PMID 34199293, 2021). "Similarly, a study showed that constitutively active NF-κB upregulates CXCR-4 expression and promotes tumor cell migration and metastasis in breast cancer cells." (PMID 33854604, 2021). "Besides, the impaired invasive potential due to CXCR4 repression by the treatment of miR-139 in breast cancer cells was confirmed via using short hairpin RNAs (shRNAs) against CXCR4 (sh-CXCR4)." (PMID 34070538, 2021). "However, more research is needed through breast cancer clinical trials to determine the efficacy of CXCR4/SDF-1α antagonists alone or in combination with other chemotherapeutic agents." (PMID 33919589, 2021). "In breast cancer cells, CXCR4 signaling induced cell migration and invasion." (PMID 34503058, 2021). "Therefore, we suggest that the CXCR4 axis is a candidate mediator of fasting‐induced CD205+ G‐MDSC reduction in breast cancer hosts." (PMID 34646521, 2021). "However, in this study, we demonstrate that there is also a role of CXCR4 on breast cancer cell migration when it is expressed on TAMs." (PMID 35111484, 2021). "Evidence revealed that the activation of CXCL12/CXCR4 could promote invasion and metastasis in breast cancer, gastric cancer 9 and glioblastoma." (PMID 34170080, 2021). "CXCR4 may also couple to G12/13, promoting metastasis in a RhoA-dependent manner in basal-like breast cancer cells." (PMID 34943797, 2021). "Breast carcinoma and melanoma metastases both have a high incidence of CXCR4 expression." (PMID 34503058, 2021). "Furthermore, other extracellular proteins involved in the CXCR4 pathway (such as HER2) show some therapeutic potential for the inhibition of breast cancer metastases." (PMID 33919589, 2021). "The CXCL12/CXCR4 axis is said to have a critical role in breast cancer metastasis." (PMID 34066014, 2021). "Indeed, TCDD, the highly toxic AhR agonist, cannot be used in the clinic to specifically target AhR, despite its positive effect against breast cancer, by disrupting the CXCR4/CXCL12 pathway, or ovarian cancer cells." (PMID 33451095, 2021). "CXCR4 is expressed in multiple cell types including macrophages and breast cancer cells." (PMID 35111484, 2021). "Several studies demonstrated that CXCR4 expression may have value in predicting breast cancer prognosis." (PMID 33986665, 2021). "Finally, by performing immunofluorescence microscopy, CXCR4 (red) protein expression was found to be predominant in human breast cancer tissues whereas, DR5 (green) expression was sparse." (PMID 33966046, 2021). "Moreover, we found elevated expression of CXCR4 in SHH signaling activated breast cancer spheres, indicating that CXCR4 expression is correlated with the activity of SHH pathway." (PMID 34052833, 2021). "Consequently, overall survival of patients with breast cancer with tumors exhibiting high RNA expression of FPR1 or CXCR4 was more impaired than that of patients with low tumor RNA expression of these molecules." (PMID 34876407, 2021). "The role of CXCR4 expression on breast cancer cells has been extensively studied." (PMID 35111484, 2021). "It has been shown that breast cancer patients with high CXCR4 expression have poor prognosis." (PMID 34198652, 2021). "Dormant breast cancer cells reside in specific bone marrow niches that regulate their entry into the bone marrow via E-selectin, while anchoring them to the microenvironment via CXCR4/CXCL12 axis." (PMID 35006432, 2021). "It has been shown that CXCR4 is abundantly expressed in breast cancer cells." (PMID 34943797, 2021). "As illustrated in the PPI network, CXCR4 as a chemokine receptor has been found to be upregulated in cancer metastasis, and it has been used as a prognostic marker in various types of cancer, including leukemia, breast cancer, and prostate cancer." (PMID 32509861, 2020).
breast carcinoma (continued). "In addition, saikosaponin A, anti-VEGF Ab and gap junction inhibitor, reduces the expression of CXCR4 in breast cancer cells." (PMID 33096815, 2020). "It has been confirmed that CXCR4 is involved in lung metastasis of breast cancer." (PMID 32253815, 2020). "In this review, we explore the role of the CXCL12/CXCR4 pathway in breast cancer." (PMID 33096815, 2020). "Additionally, leptin-induced metastasis of breast cancer cells was inhibited when the SDF-1/CXCR4 axis was blocked by AMD3100." (PMID 32836215, 2020). "Moreover, overexpression of CXCR4, HGF, and c-MET in primary breast cancer is associated with worse patient outcomes in females." (PMID 32188473, 2020). "Furthermore, CXCR4 upregulation in breast cancer cells enhanced the migratory potential of tumor cells towards SDF-1 producing organs." (PMID 32836215, 2020). "The SDF-1/CXCR4 axis activated by leptin also promoted bone metastasis of breast cancer." (PMID 32836215, 2020). "The CXCL12/CXCR4 signaling has also been a therapeutic target in breast cancer research." (PMID 33096815, 2020). "Multiple strategies aiming at blocking CXCR4 expression in breast cancer have been proposed." (PMID 33096815, 2020). "A study showed that nobiletin decreases the expression of CXCR4 in breast cancer cells." (PMID 32212785, 2020). "Since the CXCL12/CXCR4 cascade plays important roles in many aspects of breast cancer tumorigenesis, treatments aiming to inhibit this pathway might provide valuable therapeutic tools." (PMID 33096815, 2020). "Thus, CXCL12/CXCR4 blockade boosts the efficacy of immune checkpoint blockers in preclinical models of breast cancer." (PMID 33096815, 2020). "However, we reported that CXCL12 expression was significantly increased in the lung of the mouse breast cancer model, which recruited a large number of CD62Ldim neutrophils through the CXCR4/CXCL12 axis." (PMID 33178575, 2020). "This interaction reduces CXCR4-mediated ERK1/2 phosphorylation and chemotaxis suggesting that the cannabinoid signaling might decrease CXCR4 signaling and possibly breast cancer progression." (PMID 33096815, 2020). "In addition, we investigate the differences in LASP1-CXCR4 signaling in breast cancer and CML, as these two tumor entities display different roles for CXCR4, despite comparable overexpression of the receptor binding-partner LASP1." (PMID 32075106, 2020). "Furthermore, the cancer progenitor population can be maintained by CXCR4 in tamoxifen-resistant breast cancer MCF7 cells by inducing AhR signaling." (PMID 33363463, 2020). "Moreover, NF-κB alone can activate the expression of CXCR4 in metastatic breast cancer cells via direct interaction with its promoter inducing cell motility." (PMID 33096815, 2020). "In addition to the chemotaxis caused by the interaction of CXCR4/12, RANKL in bone tissue can also attract RANK-expressing circulating breast cancer cells to the bone matrix." (PMID 32117996, 2020). "Finally, the CXCL12/CXCR4 signaling induces breast cancer cell motility and is involved in all types of breast cancer metastasis." (PMID 33096815, 2020). "CXCR4 antagonist POL5551 reduces migration of TNBC breast cancer cells in vitro." (PMID 33096815, 2020). "The CXCL12/CXCR4 signaling affects both innate and adaptive immunity in breast cancer." (PMID 33096815, 2020). "Moreover, low LRP6 expression worsened already poor prognosis of patients with breast cancer and high CXCR4 levels." (PMID 33096815, 2020). "CXCL12 and its cell surface receptor CXCR4 combine to enhance the migration of breast cancer cells." (PMID 32847038, 2020). "Finally, increased CXCR4 expression was accompanied by high leptin receptor expression in bone metastatic tissues from breast cancer patients." (PMID 32836215, 2020).
breast carcinoma (continued). "In this review, we examine state-of-the-art knowledge about detrimental roles of the CXCL12/CXCR4 signaling, discuss its therapeutic potential and suggest further research directions beneficial both for basic research and personalized medicine in breast cancer." (PMID 33096815, 2020). "The effect of LASP1 on focal adhesion dynamics through its interaction with zona occludens 2 (ZO-2) and zyxin, as well as its impact on motility through association with the chemokine receptor CXCR4 and vimentin, suggests an intricate role for LASP1 in breast cancer metastasis." (PMID 32872485, 2020). "We found that leptin also significantly increased CXCR4 expression in breast cancer cells." (PMID 32836215, 2020). "pDCs secrete TNF, which induces CXCR4 expression in breast cancer cells." (PMID 33096815, 2020). "Prior studies have linked increased CXCR4 promoter cytosine methylation (5mC) to decreased CXCR4 protein expression in several non-colonic cancers such as primary breast cancer, decreased mRNA and protein in melanoma cell lines and primary cervical cancer." (PMID 32110952, 2020). "The CXCL12/CXCR4 axis compromises adjuvant therapy in breast cancer." (PMID 32079335, 2020). "In addition to its role in normal physiology, CXCR4 also plays an important role in disease progression and metastasis of several different types of solid tumors including breast cancer." (PMID 32872485, 2020). "Breast cancer e.g., was found to express the chemokine receptors CXCR4 and CCR7 at high levels." (PMID 32547940, 2020). "CXCR4 antagonists including AMD3100 could also exhibit potential against bone marrow metastasis in breast cancer." (PMID 33096815, 2020). "Interestingly, several studies have shown that CXCR4 has a key role in stimulating the chemotactic and invasive behaviour of breast cancer cells, and blocking CXCR4 prevents breast cancer metastatic spread in vitro and in vivo." (PMID 32545448, 2020). "Moreover, leptin-induced breast cancer cell metastasis was due at least in part to activation of the SDF-1/CXCR4 axis." (PMID 32836215, 2020). "The positive expression rate of CXCR4 in breast cancer is as high as 60%." (PMID 32253815, 2020). "In addition, tumor cell-derived angiopoietin-like protein 2 (Angptl2) induces CXCR4 and activates CXCL12/CXCR4 signaling in breast cancer cells, leading to bone metastasis." (PMID 33096815, 2020). "Indeed, ACKR3-dependent depletion of CXCL12 and inhibition of short-term CXCR4 signaling was observed in CXCR4-positive breast cancer cells." (PMID 32456359, 2020). "Inhibition of stromal SDF-1–dependent CXCR4 activation by CXCR4 inhibitors attenuates myofibroblast content, tumor angiogenesis, and tumor growth in patient-derived tumor xenografts from Her2+ human breast cancers." (PMID 31331982, 2019). "Similarly, tumor uptake of a 64Cu doped gold nanoclusters conjugated with AMD3100 ([64Cu]AuNCs-AMD3100) tracer correlated with CXCR4 expression in a 4T1 orthotopic mouse breast cancer." (PMID 31652624, 2019). "Moreover, miR-494 inhibits proliferation, invasion and metastasis of prostate and breast cancer cells by suppressing CXCR4 expression." (PMID 31584877, 2019). "Moreover, zerumbone downregulated CXCR4 expression on human-epidermal growth factor receptor-2 (HER2)-overexpressing breast cancer cells by abrogating NF-κB activation which correlated with the arrest of invasion and metastasis induced by CXCL12 expression." (PMID 30781671, 2019). "CXCR4/SDF-1 axis plays a vital role in breast cancer growth and metastasis." (PMID 32047724, 2019). "Indeed, exosomes secreted by C-X-C chemokine receptor type 4 (CXCR4)-overexpressing breast cancer cells exhibited high levels of stemness-related markers and metastatic-related messenger ribonucleic acids (mRNAs)." (PMID 31078138, 2019). "Additionally, we compared our data for CXCR4, which is known to be expressed in peripheral blood CTCs from breast cancer patients." (PMID 31026363, 2019).
breast carcinoma (continued). "However, the CXCR4/CXCL12 interaction is unlikely involved in the metastasis of breast cancers to the liver." (PMID 31477571, 2019). "Noteworthy, it has been reported that CXCR4 signaling could promote ER positive breast cancer to a therapy-resistant, estrogen-independent phenotype." (PMID 31652624, 2019). "Notably, it has been shown that CXCR4 was also expressed in various types of cancers including glioblastoma, liver cancer, breast cancer, and esophageal cancer." (PMID 31336612, 2019). "Moreover, in mouse mammary carcinoma model, CXCR4 was found to regulate both primary and metastatic breast cancer." (PMID 31681564, 2019). "Similarly, CCL2 expression by cancer-associated fibroblasts has been shown to support the growth of breast cancer stem cells, while CXCR4 was shown to be enriched in a subset of glioma cancer stem cells." (PMID 30873179, 2019). "Taking these proteins into account, CXCR4 could therefore have significant (and multifaceted) effects on breast cancer cells through modulation of this translational mechanism." (PMID 31106142, 2019). "In concurrence with previously published observations, this result points to a secondary CXCR4-related mechanism which may be specific to certain cancer cell types such as MDA-231 breast cancer cells." (PMID 29682200, 2018). "Importantly, a role for SDF1/CXCR4 signaling in macrophage attraction has been described before in rodent models of breast cancer and tumor relapse after chemotherapy." (PMID 29465400, 2018). "Despite the fact that the spontaneous feline mammary carcinoma (FMC) is considered a suitable model for breast cancer studies, the importance of the CXCR4/CXCL12 axis in FMC is completely unknown." (PMID 30012106, 2018). "Initial experiments showed that CXCR4 and ACKR3 were upregulated in primary breast cancer and that CXCR4 and ACKR3 could form heterodimers in transfected CHO cells." (PMID 30441765, 2018). "Evidence for a regulatory role of CXCR4/CXCL12 axis in the progression of the metastatic disease was found in breast cancer patients with the organs and tissues with highest CXCL12 expression frequently showing metastases and with CXCL12 working as a chemotactic factor." (PMID 30012106, 2018). "Furthermore, other researchers have provided several evidences of SDF1/CXCR4 co-expression in breast cancer, colorectal cancer and glioma." (PMID 29783989, 2018). "Thirteen patients with first diagnosis of breast cancer, four patients with recurrent disease after primary breast cancer, and one patient with axillary lymph node metastasis of unknown primary underwent CXCR4-targeted PET imaging using 68Ga-Pentixafor." (PMID 30191351, 2018). "Among GPCRs, CXCR4 has been indicated to play a role in breast cancer cell growth." (PMID 30109213, 2018). "On the basis of the crucial role of SDF1/CXCR4 in breast cancer metastasis to femora, tibiae, and mandibles, we systemically injected via an intracardiac route MDA-MB-231-luc+ cells to test the ability of TQ to modulate CXCR4 expression and thereby inhibit metastasis to the bones and other organs." (PMID 30564115, 2018). "Moreover, stromal-produced CXCR4/CXCL12 has been suggested to be crucial for priming breast cancer cells to metastasize to the liver." (PMID 30428629, 2018). "To confirm CXCR4 expression, first we screened for CXCR4 expression in our breast carcinoma cells lines MDA-MB-468, MDA-MB-231, MCF-7, DU4475, as well as in THP-1, HUVEC, U937, and Jurkat through RT-PCR analysis Total RNA was prepared and subjected to RT-PCR analysis to detect CXCR4-specific mRNA." (PMID 29682200, 2018). "Some of the response of breast cancer to CXCR4 may be determined by the presence of estrogen receptors, as the CXCl-12 signalling axis is important for the estrogen-mediated growth of breast cancer cells." (PMID 29098360, 2018). "Based on these results in a small patient cohort, CXCR4-targeted PET imaging does not seem to be suitable as a general diagnostic tool for imaging of breast cancer." (PMID 30191351, 2018).
breast carcinoma (continued). "Likewise, blocking the CXCL12/CXCR4 pathway during engraftment of 4T1 mammary carcinoma cells in BALB/c mice yielded similar results (1 in 496 vehicle vs. 1 in 2,466 AMD3100)." (PMID 29632733, 2018). "Our results indicated that actein could down-regulate the CXCR4 gene expression in breast cancer cells." (PMID 30618758, 2018). "Indeed, CXCR4 expression in PT promotes metastasis of CXCR4 positive tumor cells to sites commonly affected by metastatic breast cancer (lymph node, lung, liver, bone marrow and brain) where its ligand CXCL12 is generated in large quantity." (PMID 30012106, 2018). "Additionally, a recent document reported that miR-381 suppressed proliferation, EMT and metastasis of breast cancer cells through targeting CXCR4." (PMID 30309377, 2018). "Subsequent analysis using a publicly-available dataset revealed that the coordinated low-expression of CD163 and CXCR4 with high expression of THBS1 in 161 breast cancer tissues identified patients with TNBC (basal) having a high risk of recurrence and poor survival rate." (PMID 30254632, 2018). "Finally, CXCR4 siRNA was efficiently delivered into the cytoplasm of MDA-MB-231 breast cancer cells and inhibited the protein expression of CXCR4 with an efficacy comparable to that of a commercial transfection reagent." (PMID 30966561, 2018). "More recently, an extensive amount of research has been conducted to clarify the role of CXCR4/CXCL12 axis in human breast cancer and metastatic disease, suggesting that targeted therapies against CXCR4/CXCL12 axis may inhibit tumor growth." (PMID 30012106, 2018). "Therefore, new agents that can abrogate CXCR4 expression have potential against breast cancer metastasis." (PMID 30564115, 2018). "In addition to these physiological roles, CXCR4 has been found to be overexpressed by various human cancers including breast cancer." (PMID 30191351, 2018). "Furthermore, NF-κB regulates the motility of breast cancer cells by directly up-regulating the expression of CXCR4." (PMID 28402272, 2017). "In addition, irradiation-enhanced invasiveness of non-small lung cancer and breast cancer has been attributed to the SDF-1α/CXCR4 interaction." (PMID 28978091, 2017). "The present study aims to investigate the delivery efficiency of siRNA by chitosan into breast cancer cells, and then to examine the regulatory role by chitosan nanoparticle-delivered siRNA on CXCR4 expression and on the chemosensitivity of breast cancer cells." (PMID 28446538, 2017). "Several investigations report a role for the chemokine receptor CXCR4 and its ligand CXCL12 in site-specific metastasis, where neutralization of the CXCL12/CXCR4 interaction significantly impaired metastases formation in lymph nodes, bone, and lung in metastatic breast cancer models." (PMID 29037250, 2017). "CXCR4-overexpressing MSCs could be useful for SDF1α-secreting breast cancer therapeutic drug delivery." (PMID 28740515, 2017). "Additionally, siRNA knock-down of CXCR4 in breast cancer cells or neutralizing antibody against CXCR4 reduced tumor growth and inhibited metastasis." (PMID 28785589, 2017). "Indeed, the chemokine CXCL12 plays critical roles in cell migration, angiogenesis, proliferation, and survival in many types of cancer, including breast cancer, by interacting with the transmembrane receptors CXCR4 and CXCR7." (PMID 28666461, 2017). "Similarly CXCL12, a ligand of both CXCR4 and ACKR3, is associated with advanced breast cancer in humans, and is expressed at high levels during puberty and pregnancy in our study (data not shown)." (PMID 27888192, 2017). "Furthermore, neutralizing antibody directed against CXCL16, alone or in combination with CXCR4 antagonist, significantly inhibited the migration of patient-derived breast cancer cells in our 3D CAF aggregate system." (PMID 28649646, 2017).